KCNH6 (potassium voltage-gated channel subfamily H member 6)
Description:
Pore-forming (alpha) subunit of voltage-gated inwardly rectifying potassium channel. Characterized by unusual gating kinetics by producing relatively small outward currents during membrane depolarization and large inward currents during subsequent repolarization which reflect a rapid inactivation during depolarization and quick recovery from inactivation but slow deactivation (closing) during repolarization. Activates even more slowly than KCNH2.
Synonyms: ERG-2; hERG-2; hERG2; ERG2; Kv11.2
Tractability: Small molecule: an approved drug acts on it; it belongs to a druggable protein family. Antibody: its Gene Ontology location is reachable by antibodies, with high confidence; UniProt places it where antibodies can reach, with medium confidence; UniProt predicts a signal peptide or a membrane-spanning region. PROTAC: ubiquitination databases record sites on it.
Target class: Potassium channels; Ion channel; Voltage-gated ion channel; Voltage-gated potassium channel
Gene: Protein-coding gene on chromosome 17 (63,523,310 to 63,548,987, forward strand). Ensembl gene ENSG00000173826.
Subcellular location: Cell membrane
Pathways (Reactome):
Neuronal System: Voltage gated Potassium channels
Gene Ontology:
Molecular function: inward rectifier potassium channel activity; monoatomic ion channel activity; voltage-gated potassium channel activity
Biological process: membrane repolarization during cardiac muscle cell action potential; potassium ion transmembrane transport; regulation of heart rate by cardiac conduction; regulation of ventricular cardiac muscle cell membrane repolarization; monoatomic ion transport; potassium ion transport; transmembrane transport
Cellular component: plasma membrane; membrane
Genetic constraint (gnomAD): Loss-of-function variants: 82 observed, 86.45 expected, observed/expected ratio (o/e) 0.95, 90% interval 0.79 to 1.14. The upper end of that interval is the gene's LOEUF score, 1.14, which puts it in group 5 of 6, group 1 being the genes least tolerant of losing a copy. Missense variants: 1,203 observed, 1,337.6 expected, observed/expected ratio (o/e) 0.9, 90% interval 0.86 to 0.94. Synonymous variants: 503 observed, 564.72 expected, observed/expected ratio (o/e) 0.89, 90% interval 0.83 to 0.96.
Homologues: Orthologues: chimpanzee KCNH6 (99% identical), macaque KCNH6 (98% identical), pig KCNH6 (92% identical), dog KCNH6 (90% identical), mouse Kcnh6 (90% identical), rat Kcnh6 (90% identical), guinea pig KCNH6 (85% identical), rabbit KCNH6 (82% identical), tropical clawed frog kcnh6 (71% identical), Caenorhabditis elegans unc-103 (42% identical), Drosophila melanogaster sei (41% identical), Drosophila melanogaster CngA (14% identical), and 3 more. Paralogues in human: KCNH2 (65% identical), KCNH7 (62% identical), KCNH4 (36% identical), KCNH8 (35% identical), KCNH1 (32% identical), KCNH3 (32% identical), KCNH5 (32% identical), HCN4 (17% identical), HCN1 (16% identical), HCN2 (16% identical), HCN3 (16% identical), CNGA2 (15% identical), and 5 more.
Diseases named in the same sentence as KCNH6 in open-access papers:
KCNH6 is named in the same sentence as 25 diseases in open-access papers, as found by Europe PMC text mining. Sharing a sentence is not in itself a finding about the gene and the disease. The quoted sentences say what the papers report.
diabetes (8 papers, 2021 to 2024). "Previously, our group found that adult patients with hypoinsulinism and diabetes presented with a heterozygous mutation in the KCNH6 gene." (PMID 36325440, 2022). "As liver glucose metabolism is key to T2D, understanding KCNH6 functions may provide new insights into the causes of diabetes." (PMID 36217412, 2022). "Mutations in KCNH6 has been proved to cause hypoinsulinemia and diabetes in human and mice." (PMID 36325440, 2022). "The Kv inhibitor BBR has shown promise as an approach to targeting Kcnh6 and thereby treating diabetes in humans." (PMID 38510653, 2024). "This is the first study to analyse the sequence of the MTOR, TBC1D4, CACNA1E, SLC19A2 and KCNH6 genes in Polish patients with suspected MODY-X diabetes using the NGS method." (PMID 38932873, 2024). "We found that both patients with KCNH6 p.P235L heterozygous mutation and KCNH6 mutant including P235L knock in (KI) and KCNH6 global knockout (GKO) mice had a phenotype from hyperinsulinemia to hypoinsulinemia and diabetes." (PMID 38349432, 2024). "Recently, we reported one of the Kv channels, KCNH6 (also called Kv11.2 or hERG2), regulating insulin secretion through its electrical function by studying a large four-generation family with monogenic diabetes." (PMID 38349432, 2024). "Dysfunction of the voltage-gated K+ (Kv) channel KCNH6 leads to a phenotype of hyper-to hypoinsulinaemia and diabetes in both humans and mice." (PMID 39055936, 2024). "Our previous studies revealed that Kcnh6 KO mice presented with impaired glucose tolerance or diabetes, which prompted us to explore the role played by KCNH6 in glucose metabolism." (PMID 36217412, 2022). "In this study, we reported that BBR, which targeted the KCNH6 Kv channels, served as the first Kv inhibitor to treat humans with diabetes." (PMID 34556670, 2021). "BBR was administered to both HFD-fed hyperglycemic WT mice and HFD-fed hyperglycemic Kcnh6 KO mice to better examine the effect of BBR on treating diabetes." (PMID 34556670, 2021). "In this study, we identify BBR as a glucose-dependent insulin secretagogue for treating diabetes without causing hypoglycemia that targets KCNH6 channels." (PMID 34556670, 2021). "In this work, we find that blockade of KCNH6 channels by BBR increases insulin secretion in a high-glucose-dependent manner or only under hyperglycemic conditions, suggesting that BBR is a glucose-dependent insulin secretagogue for the treatment of diabetes that does not cause hypoglycemia." (PMID 34556670, 2021).
Hyperglycemia (3 papers, 2021 to 2024). An increased concentration of glucose in the blood. "Previously, our group found that dysfunction of the KCNH6 gene caused hypoinsulinemia and hyperglycemia." (PMID 36325440, 2022). "However, in mice with hyperglycemia induced by global or pancreatic islet β-cell-specific Kcnh6 knockout, BBR does not exert beneficial effects." (PMID 34556670, 2021).
Hypoglycemia (3 papers, 2021 to 2023). A decreased concentration of glucose in the blood. "Although our study revealed that KCNH6 plays an important role in cisapride-induced hypoglycemia, there are still some limitations." (PMID 36325440, 2022). "Further experiments showed that KCNH6 played a key role in cisapride-induced hypoglycemia." (PMID 36325440, 2022). "The blockade of KCNH6 channels with berberine increased insulin secretion, but only under hyperglycemic conditions, suggesting that berberine is a glucose-dependent insulin secretagogue that does not cause hypoglycemia or affects basal insulin secretion." (PMID 37513825, 2023). "Thus, KCNH6 plays a cruial role in cisapride-induced hypoglycemia." (PMID 36325440, 2022). "Thus, our data reveal a novel way for the effect of KCNH6 in cisapride-induced hypoglycemia." (PMID 36325440, 2022).
Hypoinsulinemia (3 papers, 2021 to 2024). A decreased concentration of insulin in the blood. "Our previous study reported that KCNH6 global knockout (GKO) mice exhibited early-stage hyperinsulinemia and hypoinsulinemia in later adulthood." (PMID 38349432, 2024).
Impaired glucose tolerance (2 papers, 2022 to 2024). An abnormal resistance to glucose, i.e., a reduction in the ability to maintain glucose levels in the blood stream within normal limits following oral or intravenous administration of glucose. "Interestingly, KCNH6-βKO mice exhibited impaired glucose tolerance and lower serum insulin concentrations after glucose loading which was different from those of KCNH6 GKO mice." (PMID 38349432, 2024). "However, we found that KCNH6-βKO mice exhibited severe phenotype of impaired glucose tolerance and insulin secretion even at 8 weeks age which was different from those of KCNH6 GKO mice." (PMID 38349432, 2024).
pulmonary fibrosis (2 papers, 2023 to 2025). Chronic progressive interstitial lung disorder characterized by the replacement of the lung tissue by connective tissue, leading to progressive dyspnea, respiratory failure, or right heart failure. "In pulmonary fibrosis, METTL3 drives fibroblast activation and ECM deposition via selective m6A programs, with the KCNH6-YTHDF1 axis linked to myofibroblast transition." (PMID 41515964, 2025). "METTL3 promotes the YTHDF1-dependent translation of KCNH6, thereby accelerating EMT and myofibroblast proliferation, worsening idiopathic pulmonary fibrosis (IPF)." (PMID 41515964, 2025). "Pulmonary fibrosis: Targeting METTL3-dependent myofibroblast programs (e.g., KCNH6–YTHDF1) may synergize with approved anti-fibrotics; staged designs can separate injury and remodeling phases." (PMID 41515964, 2025). "In bleomycin‐treated mice, upregulated METTL3 has been identified to enhance the m6A modification of KCNH6 mRNA in a YTHDF1‐dependent manner to promote its translation and expression, which evokes the phenotypic conversion of alveolar myofibroblasts and pulmonary fibrosis." (PMID 37537731, 2023). "In airway and alveolar epithelium, METTL3 targets SOCS3/STAT3, ACSL4, KCNH6, PTEN and others to promote epithelial–mesenchymal transition, ferroptosis and barrier disruption, thereby tightly coupling inflammatory signaling to structural remodeling in COPD, pulmonary fibrosis and ALI/ARDS." (PMID 41515964, 2025).
congenital heart disease (1 paper, 2022). A heart disease that is present at birth. "By examining candidate genes of congenital heart disease and heterotaxy, we identify KCNH6, a member of the ether-a-go-go class of potassium channels that hyperpolarizes the Vm and thus limits the activation of voltage gated calcium channels, lowering intracellular calcium." (PMID 36335122, 2022).
glucose metabolism (1 paper, 2022). "Here, we found that Kcnh6 attenuated glucose metabolism disorders by decreasing PEPCK and G6pase abundance and induced Glut2 and IRS2 expression." (PMID 36217412, 2022). "Our results indicated that KCNH6 expression attenuated glucose metabolism disorders by decreasing PEPCK and G6pase expression and inducing Glut2 and IRS2 expression." (PMID 36217412, 2022). "Experiments demonstrated that Kcnh6 expression improved hepatic glucose metabolism disorder through the c-Jun N-terminal kinase and p38MAPK signaling pathways." (PMID 36217412, 2022).
glucose metabolism disorders (1 paper, 2022). "As expected, the restoration of Kcnh6 expression reversed the glucose metabolism disorder in the KO mice." (PMID 36217412, 2022). "Adult Kcnh6 knockout (KO) mice showed glucose metabolism disorders, as indicated by significantly elevated oxidative stress and mitochondrial calcium levels." (PMID 36217412, 2022). "Here, we found that global Kcnh6 KO mice presented with liver glucose metabolism disorders." (PMID 36217412, 2022). "Hepatic glucose metabolism disorders in KO mice prompted us to investigate whether KCNH6 overexpression reverses glucose metabolism disorders." (PMID 36217412, 2022).
tumor (5 papers, 2017 to 2024). "Here, Kcnh6 upregulation was observed in the lungs of miR-147−/− mice, and associated transcriptomic changes were enriched in tumor-associated signaling pathways." (PMID 38510653, 2024). "The copy number gains observed for NGF and KCNH6 also have a low probability of being driver mutations of DFT1 as they are not on a chromosome posited to be initially involved in the formation of the tumour." (PMID 28821767, 2017).
heart disease (1 paper, 2013). "Six candidate genes including LMNA, Zinc Finger Homeobox 3 (ZFHX3), Matrix Metallopeptidase 2 (MMP2), Angiopoietin-Like 5 (ANGPTL5), Myosin Heavy Chain 7B (MYH7B) and Potassium voltage-gated channel subfamily H member 6 (KCNH6) have been previously linked to heart disease." (PMID 24349489, 2013).
KCNH6 also shares sentences with these, for which no sentence is quoted: infection (5 papers); meningioma (2); pterygium (2); atherosclerosis (1); Autoimmunity (1); brain ischemia (1); esophageal cancer (1); glioma (1); Glucose intolerance (1); Hyperinsulinemia (1); idiopathic pulmonary fibrosis (1); lupus-like syndrome (1); metabolic disorder (1); psychotic disorder (1).